CSPG4 (chondroitin sulfate proteoglycan 4)
Diseases named in the same sentence as CSPG4 in open-access papers (continued):
Sharing a sentence is not in itself a finding about the gene and the disease.
thyroid cancer (6 papers, 2023 to 2025). "NG2 (CSPG4) has been implicated in various cancers, including melanoma, glioblastoma and thyroid cancer, where its high expression correlates with poor prognosis due to its support of tumor growth, angiogenesis and resistance to therapies." (PMID 39874138, 2025). "We demonstrated that thyroid cancer cells are specifically recognized and effectively eradicated in vitro by CSPG4-targeted and B7-H3-targeted CAR T cells." (PMID 40847369, 2025). "To investigate the potential clinical relevance of targeting CSPG4, we first evaluated its expression profile across thyroid cancers." (PMID 40847369, 2025). "Next, we tested the in vitro antitumor activity of CSPG4 CAR T cells by co-culturing them with thyroid cancer cells at multiple effector (CAR T) to target (cancer cells) (E: T) ratios, ranging from 1:1 to 1:32." (PMID 40847369, 2025). "We confirmed a high and homogeneous gene and protein expression of B7-H3 and CSPG4 in different types of thyroid cancers." (PMID 40847369, 2025). "To investigate the in vitro antitumor activity of CSPG4-targeted CAR T cells, we first assessed CSPG4 membrane expression on 4 human thyroid cancer cell lines, including 8505c and SW1736 (ATC), 2 C-HCC (hurthle cell carcinoma) and BCPAP (PTC)." (PMID 40847369, 2025). "Overall, in this study we identified CSPG4 and B7-H3 as valuable target antigens in thyroid cancer and demonstrated that CAR T cell immunotherapy can be a valuable therapeutic option for ATC patients." (PMID 40847369, 2025). "Overall, in this study we identified CSPG4 and B7-H3 as valuable therapeutic targets in different types of thyroid carcinoma, including anaplastic thyroid cancer, a rare and lethal disease with no effective treatment." (PMID 40847369, 2025). "There is a strong correlation between CSPG4 expression and poor prognosis in aggressive thyroid cancers." (PMID 39664392, 2024). "To determine whether high mRNA levels correlate with protein expression, we evaluated the presence of CSPG4 on human tissue samples of thyroid cancers." (PMID 40847369, 2025). "One potential explanation could be related to the higher expression level of B7-H3 on thyroid cancer cells as compared to CSPG4, which might lead to a stronger CAR T cell activation." (PMID 40847369, 2025). "The hypothesis that CAR T cell-mediated killing correlates with the level of antigen expression is supported by the positive correlation observed between the expression levels of CSPG4 and B7-H3 on thyroid cancer cells and CAR T cell-mediated killing in vitro." (PMID 40847369, 2025). "Therefore, drugs targeting the candidate antigen, CSPG4, can potentially be used to treat thyroid cancers." (PMID 37854594, 2023). "Here, we find that nerve/glial antigen 2 (NG2), also known as chondroitin sulfate proteoglycan 4 (CSPG4), is up-regulated in thyroid cancers, and its expression is increased with tumor progression in a BRAFV600E-driven thyroid cancer mouse model." (PMID 38795180, 2024). "As target tumor antigens of our CAR T cell therapy, we selected the chondroitin sulfate proteoglycan 4 (CSPG4) and the B7-homolog 3 (B7-H3), as they are both highly and homogeneously expressed on different types of thyroid carcinoma cell lines and tissues, including ATC." (PMID 40847369, 2025). "The available evidence showing that B7-H3 and CSPG4 are highly expressed in human ATC cell lines and tumors with a limited distribution on adjacent normal thyroid tissue, prompted us to investigate the antitumor efficacy of our CAR T cell therapies with thyroid cancers, including ATC." (PMID 40847369, 2025).
astrocytomas (5 papers, 2010 to 2025). "Intriguingly, other fate-restricted cell populations have been linked to tumor initiation and have been shown for astrocytes in astrocytoma and chondroitin sulfate proteoglycan 4 (NG2)-positive OPCs in oligodendrogliomas." (PMID 34012965, 2021). "PDGFRs have been found to be overexpressed in human malignant astrocytomas; moreover, expression of NG2/CSPG4 and PDGFRα was identified in oligodendrogliomas, pilocytic astrocytomas and, heterogeneously, in GBs." (PMID 30213051, 2018).
brain tumors (5 papers, 2013 to 2022). "In brain tumors, expression levels of proteoglycans are highly regulated, such as CSPG4/NG2, PTPRZ1, CD44, aggrecan, brevican, and versican." (PMID 35920986, 2022). "High levels of CSPG4 are found on a variety of adult and pediatric solid tumors including melanoma, osteosarcoma, rhabdomyosarcoma and some brain tumors." (PMID 32231047, 2020). "The CSPG4 expression levels differ depending on tumor type but is often present in both high-grade and lower-grade pediatric brain tumors." (PMID 32231047, 2020). "Many collagens (collagens I, IV, VI) and GAGs (CSPG4, HA) are known to be upregulated in brain tumors in comparison to mature adult brain." (PMID 31586101, 2019). "Compared to adjacent non-tumor tissues, CSPG4 was overexpressed in all brain tumors samples." (PMID 25197555, 2014).
lung cancer (5 papers, 2014 to 2026). A malignant neoplasm involving the lung. "Furthermore, NG2/CSPG4-expressing cells as PCs, also known as mural cells, are important cellular components not only in the normal blood vasculature but also in the progression of solid organ cancers, such as pancreatic cancer and lung cancer." (PMID 35891187, 2022). "Furthermore, the increased tumor progression seen in a KRAS-driven lung cancer model upon HIF2a depletion (i.e., HIF2a as a tumor suppressor) is in line with the CSPG4’s lack of pro-malignant features." (PMID 24932730, 2014).
cutaneous melanoma (4 papers, 2013 to 2023). A primary melanoma arising from atypical melanocytes in the skin. "Recently, two large prospective studies also evaluated the prognostic significance of MCAM/CSPG4-positive CTCs in cutaneous melanoma." (PMID 32984308, 2020). "CSPG4 is a well-established CAR target in cutaneous melanoma." (PMID 31195686, 2019). "The use of CSPG4 in diagnosis of desmoplastic melanoma could potentially be very useful, as these lesions display unusual spindle cell morphology and lack the common clinical and histological characteristics of cutaneous melanoma, which complicates diagnosis." (PMID 24069584, 2013). "However, to our knowledge, none of the major studies on CSPG4-positive CTCs in cutaneous melanoma have yet found any correlation between CTC levels and BRAF-mutational status or adjuvant therapy." (PMID 32984308, 2020).
oligodendroglioma (4 papers, 2018 to 2022). A well-differentiated (WHO grade II), diffusely infiltrating neuroglial tumor, typically located in the cerebral hemispheres. "The expression of NG2/CSPG4 has been observed in vascular pericytes, oligodendroglioma, endothelial cells, and a subpopulation of GBM cells." (PMID 36305981, 2022). "The highest NG2/CSPG4 expression in oligodendrogliomas, if compared to the most frequent astrocytic tumors, would suggest that oligodendroglial cells exhibit the hallmarks of progenitors rather than of neural stem cells (NSCs)." (PMID 32599896, 2020). "NG2/CSPG4 marks OPCs in approximately 60% of the oligodendrogliomas." (PMID 32599896, 2020). "In 13/22 (59.1%) IDH-mutant/1p19q-codel oligodendrogliomas, tumor cells expressed NG2/CSPG4, either focally or diffusely, with a slight prevalence in grade III tumors (6/8, 75%) compared to grade II tumors (7/14, 50%), mainly in infiltration areas." (PMID 32599896, 2020).
acute myeloid leukemia (3 papers, 2017 to 2023). Acute myeloid leukemia (AML) is a group of neoplasms arising from precursor cells committed to the myeloid cell-line differentiation. "Chondroitin sulfate proteoglycan 4 expression has also been reported in acute myeloid leukemia and acute lymphoblastic leukemia (ALL), while it is not expressed on normal lymphocytes, granulocytes or hematopoietic progenitor cells." (PMID 29375561, 2017).
bladder cancer (3 papers, 2021 to 2025). "We identified CSPG4 was obviously enriched in cancer-related pathways and functions including the bladder cancer pathway (hsa05219) and TGF-β signaling pathway (hsa04350)." (PMID 35127724, 2021). "Similarly, CSPG4 is a key gene associated with EMT, energy metabolism, prognosis, and immune infiltration in bladder cancer, with high expression correlating with poorer prognosis." (PMID 41153362, 2025).
head and neck cancer (3 papers, 2017 to 2025). A primary or metastatic malignant neoplasm affecting the head and neck. "Furthermore, a CAR-T cell therapy targeting CSPG4 is currently used in a phase I clinical trial for head and neck cancer (NCT06096038), suggesting CSPG4-targeting CARs are specific with minimal off-target effects." (PMID 40082557, 2025).
malignant glioma (3 papers, 2020 to 2024). A grade III or grade IV glioma arising from the central nervous system. "NG2/CSPG4 immunoreactivity was significantly associated with EGFR gene amplification (p = 0.0005, Fisher’s exact test) in malignant gliomas and with 1p/19q-codeletion in oligodendroglial tumors (p = 0.0297, Fisher’s exact test)." (PMID 32599896, 2020). "This study presents a novel function of CS and CSPG4 as a niche factor for GICs and suggests that CS–CSPG4 may be a novel clinical target for treating malignant glioma." (PMID 38309500, 2024). "This study demonstrates a novel function of CS on CSPG4 as a niche factor, so-called “glyco-niche” for GICs, and suggests that CS–CSPG4 could be a potential target for malignant glioma." (PMID 38309500, 2024).
pancreatic cancer (3 papers, 2014 to 2022). "Although pro-stromal and pro-malignant, CSPG4 was not yet considered as a pathogenic factor or biomarker in pancreatic cancer; a stroma-rich aggressive malignancy." (PMID 24932730, 2014). "We assessed whether the shed ectodomain of CSPG4 (sCSPG4) might circulate and reflect potential changes in CSPG4 tissue expression (pCSPG4) due to desmoplastic and malignant aberrations occurring in pancreatic tumors." (PMID 24932730, 2014). "First, neither CSPG4low HPDE cells nor pancreatic cancer cell lines showed significant elevation of CSPG4 expression, although hypoxia greatly increased expression of other hypoxic markers, such as BNIP3, EPO (data not shown), and NIX." (PMID 24932730, 2014). "Proliferation, motility and invasion were neither reduced nor promoted (data not shown), questioning any role of CSPG4 in pancreatic cancer other than as a biomarker." (PMID 24932730, 2014). "Thus, pancreatic cancer cells rarely overexpressed CSPG4 and tended to retain it on the surface without shedding." (PMID 24932730, 2014).
renal cell carcinoma (3 papers, 2022 to 2024). "Strikingly, despite high CSPG4 mRNA expression in the TCGA dataset none of the 12 tested renal cell cancer cell lines expressed CSPG4 as determined by flow cytometry." (PMID 37849763, 2023).
schizophrenia (3 papers, 2019 to 2022). A major psychotic disorder characterized by abnormalities in the perception or expression of reality. "We identified two different rare missense mutations in CSPG4 exhibiting familial segregation with schizophrenia." (PMID 29302076, 2019). "Additional follow-up studies in larger cohorts will be required to definitively evaluate the association between schizophrenia and rare CSPG4 variants." (PMID 29302076, 2019). "Using a family-based genetic approach, we observed multiple rare missense mutations in CSPG4 that segregate with schizophrenia." (PMID 29302076, 2019). "A rare missense mutation found in the human CSPG4 gene has also been linked to reduced brain white matter integrity, and it has been suggested that in this instance misfunction of CSPG4 is a possible driver of familial schizophrenia." (PMID 36428658, 2022). "A previous study identified suggestive linkage at chromosome 15q22-24, containing CSPG4, in a cohort of 175 families with schizophrenia or schizoaffective disorder of Central American/Hispanic origin." (PMID 29302076, 2019). "Moreover, diffusion tensor imaging (DTI) of CSPG4 mutation carriers confirmed a global impairment in white matter integrity, together providing support for OPC dysfunction as a candidate pathophysiological mechanism of schizophrenia." (PMID 29302076, 2019).
acute leukemia (2 papers, 2014 to 2022). A clonal (malignant) hematopoietic disorder with an acute onset, affecting the bone marrow and the peripheral blood. "Moreover, the sensitivity and specificity associated with CSPG4 expression in KMT2A-r acute leukemias is controversial, and many patients harboring KMT2A-r lack its expression." (PMID 35734412, 2022). "Further studies have confirmed the association between CSPG4 expression and KMT2A-r in acute leukemia." (PMID 35734412, 2022). "Further studies are needed in order to validate these markers and to translate their application into the routine diagnostics of acute leukemia, such as comparing its predictive value compared to CSPG4/NG2 by immunophenotyping." (PMID 35734412, 2022). "Thus, although CSPG4 expression has been widely used for the prediction of KMT2A-r so far, machine learning analyses using transcriptomic data currently allow us to agnostically identify novel markers associated with most acute leukemia cases with KMT2A-r." (PMID 35734412, 2022).
anaplastic thyroid cancer (2 papers, 2023 to 2025). "Overall, our findings strongly support further investigation for the clinical translation of B7-H3- and CSPG4-targeted CAR T cell-based immunotherapies for the treatment of anaplastic thyroid cancer." (PMID 40847369, 2025). "We started by assessing CSPG4 mRNA expression level by utilizing a publicly available database (accession number GSE126698) which includes human samples of anaplastic thyroid cancer (ATC), follicular thyroid carcinoma (FTC), papillary thyroid carcinoma (PTC), and normal thyroid tissues as control." (PMID 40847369, 2025). "In this study, we demonstrate the preclinical therapeutic potential of targeting CSPG4 and B7-H3 with CAR T cells for the treatment of anaplastic thyroid cancer." (PMID 40847369, 2025).
Autoimmunity (2 papers, 2017 to 2023). The occurrence of an immune reaction against the organism's own cells or tissues. "None of these naturally occurring anti-CSPG4 T-cell responses were recognizably associated with autoimmunity." (PMID 37849763, 2023).
breast tumors (2 papers, 2012 to 2023). "Moreover, strategies using mAbs against CSPG4 could be effective against both primary breast tumors and their metastases." (PMID 36768830, 2023). "Although the mechanism of expression of CSPG4 in basal and Luminal A tumors was not fully characterized, these results suggest that CSPG4 may serve as a target not only for basal but also Luminal A breast tumors." (PMID 22984505, 2012).
conjunctival melanoma (2 papers, 2022 to 2025). "Another, study, showed that although expression of CSPG4 was higher in non-malignant naevi, a lower level of expression of CSPG4 in conjunctival melanoma was associated with higher risk of recurrence." (PMID 36428658, 2022).
lymphoma (2 papers, 2017 to 2018). A malignant (clonal) proliferation of B- lymphocytes or T- lymphocytes which involves the lymph nodes, bone marrow and/or extranodal sites. "Brehm and co-workers screened their αMCSP-ETA′ compound for differential binding and cytotoxic activity towards notoriously aggressive CSPG4+ eRMS and aRMS cell lines (RD, FL-OH1, TE-671 and Rh30) versus a CSPG4-negative lymphoma line." (PMID 28657611, 2017).
metastatic disease (2 papers, 2018 to 2023). "Clinical treatment with CSPG4-targeted 212Pb-RICs would be relevant for adjuvant settings after resection of the primary macroscopic tumor, or in treating early stages of recurrent or metastatic disease, when microscopic populations of malignant cells are present." (PMID 29561763, 2018).
oligodendroglial tumor (2 papers, 2018 to 2020). Oligodendrogliomas are cerebral tumors that are differentiated from other gliomas on the basis of their unique genetic characteristics and better response to chemotherapy. "NG2/CSPG4 distribution does not correspond to that of Olig2, that marks oligodendroglial nuclei in normal brain, and in oligodendroglial tumors and, to a lesser extent, in astrocytic tumors, being mutually exclusive with GFAP." (PMID 30213051, 2018). "Finally, the significant association between NG2/CSPG4 immunoreactivity and EGFR gene amplification (a well-known negative prognostic marker) in both astrocytic and oligodendroglial tumors is in line with previous findings." (PMID 32599896, 2020).
psoriasis (2 papers, 2017 to 2024). An autoimmune condition characterized by red, well-delineated plaques with silvery scales that are usually on the extensor surfaces and scalp. "Only B6 mice, for example, showed significantly decreased expression of Fcer2, Cspg4, Lsp1, and Aldh1b1 with IMQ treatment to recapitulate expression shifts unique to psoriasis lesions." (PMID 28279190, 2017).
anaphylaxis (1 paper, 2023). An acute hypersensitivity reaction that occurs from exposure to an allergen. "In this model, repeated administration of a surrogate rat CSPG4 IgE to immunocompetent rats did not trigger overt toxicities or anaphylaxis." (PMID 37185332, 2023).
astrocytic tumor (1 paper, 2020). A glial tumor of the brain or spinal cord showing astrocytic differentiation. "In astrocytic tumors, the Kaplan–Meier survival analysis revealed a shorter median survival time for NG2/CSPG4-positive cases (n = 4, 16 months) compared to NG2/CSPG4-negative ones (n = 20, 19 months), but the difference was not statistically significant (data not shown)." (PMID 32599896, 2020).
basophilic leukemia (1 paper, 2022). "Flow cytometry studies indicated comparable binding profiles of both light chain-purified (KS-IgE) and IgE class-specific affinity-purified CSPG4-IgE (CS-IgE) to rat basophilic leukemia cell line RBL-SX38 cells expressing the high-affinity human IgE receptor FcεRI." (PMID 36362241, 2022).
benign adenoma (1 paper, 2014). "It transpires that pancreatic CSPG4 overexpression is a robust feature of a stroma-poor benign adenoma SCA." (PMID 24932730, 2014).
bladder tumors (1 paper, 2023). "Immunohistochemical assays demonstrated differential expression of CSPG4 in bladder tumors and normal bladder tissues, with high CSPG4 expression correlating with a poorer BLCA prognosis." (PMID 38015710, 2023).
bone metastasis (1 paper, 2022). Transfer of a neoplasm from its primary site to bones. "In the current analyses, CSPG4 was positively associated with CD34 and HIF1A, together with the previous report on the role of CSPG4 in angiogenesis, CSPG4 tends to be a promising molecule to be evaluated for its involvement in bone metastasis related angiogenesis." (PMID 35685372, 2022).
brain ischemia (1 paper, 2020). Diminished or absent blood supply to the brain caused by obstruction (thrombosis or embolism) of an artery resulting in neurologic damage. "In present study, we first found that cerebral ischemia could cause more severe brain damage in Cspg4‐Cre; senp1f/f mice than control mice, including infarct volume, motor deficits, NUV injury, and vascular thrombosis." (PMID 32495523, 2020). "The expression of active fragmentation of CaN was increased significantly in the penumbra in Cspg4‐Cre; senp1f/f mice after cerebral ischemia." (PMID 32495523, 2020). "The latency of the rotarod test was markedly decreased in Cspg4‐Cre; senp1f/f mice after cerebral ischemia." (PMID 32495523, 2020). "We first reported SENP1 in pericytes played a protective role in cerebral ischemia with Cspg4‐Cre; senp1f/f mice." (PMID 32495523, 2020). "Similarly, the fragmentation of spectrin accumulated in Cspg4‐Cre; senp1f/f mice after cerebral ischemia." (PMID 32495523, 2020).
cancers of the liver (1 paper, 2022). "Since then, many studies have demonstrated that NG2/CSPG4 is also a marker of immature cell types outside the CNS, which correlates with solid organ malignancies, such as cancers of the liver, pancreas, lungs, and kidneys." (PMID 35891187, 2022).